REG3A (regenerating family member 3 alpha)
Diseases named in the same sentence as REG3A in open-access papers (continued):
Sharing a sentence is not in itself a finding about the gene and the disease.
colitis (12 papers, 2012 to 2025). Inflammation of the colon. "Their expression is frequently dysregulated in conditions such as pancreatitis, colitis, hepatitis, and cirrhosis, where REG3A appears to function as part of a feedback mechanism aimed at dampening inflammation." (PMID 40723277, 2025). "At least for one of these genes, clec-52, this involvement may be conserved, as enteric delivery of the human clec-52 homolog Reg3A in mice was shown to alter gut microbiome composition and to reduce colitis." (PMID 39878514, 2025). "Notably, REG3A was shown to decrease ROS levels in the gut microbiota of mice with colitis and enhance the survival of oxygen-sensitive, Gram-positive Clostridia in vitro, suggesting that its antioxidant activity contributes to microbiota modulation." (PMID 40723277, 2025). "We examined this idea further by determining the expressions of genes encoding four antimicrobial proteins (regenerating islet-derived [Reg] family protein 2, Reg3α, Reg3β, and Reg3γ) in the pancreas of DSS-colitis mice." (PMID 33594081, 2021).
colorectal cancer (10 papers, 2011 to 2025). A primary or metastatic malignant neoplasm that affects the colon or rectum. "And up-regulation of Reg3A was found in the tumors with high-level colonization by Fusobacterium, a kind of colorectal cancer-associated bacteria." (PMID 31921694, 2019). "The most compelling evidence for the dualistic nature of REG3A comes from studies in gastric and colorectal cancers, where its role oscillates between tumor-suppressive and oncogenic depending on experimental conditions and disease characteristics." (PMID 40723277, 2025). "In colorectal cancer, REG3A forms an RNA–DNA triplex with lncRNA REG1CP to promote cancer cell-cycle progression and tumorigenicity and is associated with poor patient outcomes." (PMID 34811636, 2022). "Reg1cp belongs to Reg family and has been reported to promote colorectal cancer cell proliferation through activation of REG3A in colon cells." (PMID 36302749, 2022). "In comparing 79 colorectal tumors to their matched normal mucosas, Reg3A gene in colorectal cancer tissues was up-regulated by 23-fold." (PMID 31921694, 2019). "Transfection with siRNAs targeting Reg3A resulted in the inhibited proliferation of colorectal cancer LOVO and RKO cells." (PMID 31921694, 2019). "This study also explore the effect of Reg3A silence in colorectal cancer cells on tumor growth in nude mice." (PMID 31921694, 2019). "• The results from co-immunoprecipitation experiments using Reg3A antibody in colorectal cancer LOVO and RKO cells indicated that the endogenous fibronectin 1 and Reg3A were immunoprecipitated by Reg3A antibody, but not by the control IgG." (PMID 31921694, 2019). "Moreover, in gastrointestinal carcinomas, elevated levels of REG3A were correlated with increased tumour burden, tumour staging, and lower survival rate in patients with colorectal cancer." (PMID 39337456, 2024). "Furthermore, upregulation of REG3A in colorectal cancer cells was correlated with larger tumor size, poorer differentiation, higher tumor stage, and lower survival rate." (PMID 34811636, 2022). "In addition, REG3A expression level was significantly higher in colorectal cancer tissues than in normal colon tissues." (PMID 33194689, 2020). "However, the present study found that REG3A correlates with favorable survival in colorectal cancer, and is down-regulated in primary tumors of patients with distant metastasis (M1) compared to patients without distant metastasis (M0)." (PMID 33194689, 2020). "Up to date, Reg3A has been considered as a promising tumor marker and a novel intervention target for many kinds of gastrointestinal cancer, including pancreatic, liver, gastric, and colorectal cancer." (PMID 31921694, 2019). "Interestingly, REG3A was found to promote cell proliferation in gastric and colorectal cancers." (PMID 33194689, 2020). "REG1CP is notably upregulated in both preneoplastic colonic lesions and colorectal carcinomas, suggesting a cooperative axis between REG1CP and REG3A in promoting colorectal tumorigenesis." (PMID 40723277, 2025). "In contrast to the epigenetic regulation of gene expression, lncRNA REG1CP, which is overexpressed in colorectal cancers, recruits FANCJ (Fanconi anemia of complementation group J) helicase at the REG3A (regenerating family member 3 alpha) promoter region." (PMID 36010595, 2022). "On the contrary, the proliferation abilities of colorectal cancer HT-29 and SW116 cells were enhanced by Reg3A overexpression." (PMID 31921694, 2019).
diabetes (10 papers, 2014 to 2025). "Similar to Reg1, Reg3a and Reg3b have been associated with islet regeneration and protection against diabetes." (PMID 24465846, 2014). "In the unhealthy population they co-occur with REG1A, REG1B, CPB1, and REG3A, all involved in diabetes mellitus and malignant neoplasms." (PMID 37021928, 2023). "Here the authors report that REG3A inhibits TLR3-driven inflammation in skin wounds, and show that REG3A is reduced in models of diabetes, which exacerbates inflammation in diabetic wounds." (PMID 27830702, 2016). "Here we show that this balance is impaired at the epithelial surface in the context of diabetes, and that innate immune system uses REG3A to enable the control of this balance during wound healing." (PMID 27830702, 2016). "We then confirmed that decreased REG3A expression was possibly due to decreased IL-33 in diabetic skin wounds, as the administration of IL-33 into the dorsal skin of diabetes restored RegIIIγ expression." (PMID 27830702, 2016). "Altogether, these data confirm that RegIIIγ is required for the control of inflammatory responses in skin wounds, and that defective REG3A/RegIIIγ expression leads to impaired wound healing in diabetes." (PMID 27830702, 2016). "REG3A, in particular, has emerged as a critical factor in pancreatic regeneration and β-cell protection, positioning it as a potential therapeutic target in diabetes and metabolic disorders." (PMID 40723277, 2025). "Because insulin resistance in skeletal muscle is the major disruption of insulin action in type 2 diabetes, increasing muscle action of REG3A may contribute to the decrease of insulin resistance in diabetes and obesity." (PMID 36918710, 2023). "Recently, emerging evidence has demonstrated the differential expression of REG3A in patients with diabetes, inflammatory bowel disease (IBD), and cancers, which may suggest an important physiological function of REG3A." (PMID 34811636, 2022). "We thereby hypothesized that impaired wound healing in diabetes might correlate with an aberrant REG3A expression." (PMID 27830702, 2016). "Here we observed that defective REG3A expression may impair wound healing in diabetes through the exacerbation of TLR3-mediated inflammation." (PMID 27830702, 2016). "The reduction of cutaneous REG3A, possibly as a consequence of decreased IL-17-induced IL-33 caused by hyperglycaemia, will therefore lead to excessive production of TLR3-mediated pro-inflammatory cytokines observed in diabetes after skin trauma." (PMID 27830702, 2016). "However, in the context of diabetes, the expression of REG3A was impaired in skin wounds and SHP-1 was observed to be diminished in parallel, thus leading to excessive production of TNF-α and IL-6 and delayed wound healing." (PMID 27830702, 2016). "The identification of REG3A functions in skin provides novel insights into pathways contributing to wound repair in diabetes and may ultimately lead to the development of immunomodulatory strategies for the treatment with diabetic skin wounds." (PMID 27830702, 2016). "Both of these functions of REG3A link this system to essential processes involved in wound healing and suggest that REG3A could be a potential drug for the treatment with delayed or unhealed skin wounds of patients with diabetes." (PMID 27830702, 2016). "Thus, the identification of REG3A as a mediator for inflammatory responses in skin wounds, and the elucidation of its mechanism of action, provides crucial information for understanding the process of wound healing in diabetes." (PMID 27830702, 2016). "There is an increased expression of Reg2 in the total pancreas of NOD mice during diabetes development and staining of the 10-week old NOD pancreas showed expression of Reg 1, 2 and Reg3α, -γ proteins in the islets." (PMID 25166904, 2014).
diabetes (continued). "One such example involves INGAP peptide (INGAPpp), a structural homolog of REG3A derived from hamster, which has been evaluated in two randomized, placebo-controlled Phase II clinical trials targeting diabetes mellitus." (PMID 40723277, 2025). "Notably, administration of INGAPpp, a pentadecapeptide derived from hamster REG3A, has been shown to increase islet volume and cell mass in diabetic models, preventing streptozotocin (STZ)-induced diabetes without directly stimulating cell proliferation." (PMID 40723277, 2025).
acute GVHD (9 papers, 2013 to 2023). "Thirty patients that were identified as high risk for steroid refractory acute GVHD determined by a composite risk score that included measurement of Reg3α and ST2." (PMID 34899738, 2021). "The Mount Sinai Acute GVHD International Consortium (MAGIC) algorithm probability score (MAP score) based on plasma ST2 and REG3α is a response biomarker for acute GVHD." (PMID 36817455, 2023). "ST2 and Reg3a were measured in plasma samples compared in patients with acute GVHD and the controls." (PMID 32927932, 2021). "The aim of the present study was to investigate the potential role of two markers, Suppression of tumorigenicity 2 (ST2) and Regenerating islet-derived protein 3 alpha (Reg3a), in the prediction of acute GVHD." (PMID 32927932, 2021). "A recent study nicely demonstrated the role of the Paneth cell derived protein Regenerating islet-derived protein 3 alpha (REG3α) to regulate GI acute GVHD." (PMID 30705680, 2018). "In non-myeloablative transplants, elevated plasma ST2, REG3α, and elafin measured early post-transplant were predictive of acute GVHD." (PMID 36817455, 2023). "Similarly, in patients who developed acute GVHD (all grades included), D28 ST2, and REG3α as well as D14 ICAM1 were significantly higher compared to those without GVHD." (PMID 32885223, 2020). "Similarly, in T-replete haplotransplants, elevated plasma ST2 and REG3α measured early post-transplant were predictive of acute GVHD and non-relapse mortality." (PMID 36817455, 2023).
Hyperglycemia (8 papers, 2016 to 2025). An increased concentration of glucose in the blood. "Our results clarify the role of high glucose in the inhibition of IL-17-induced IL-33 expression via glucose glycation in keratinocytes and reveal that hyperglycaemia is a possible causative mechanism of decreased REG3A by IL-33 in diabetic skin wounds." (PMID 27830702, 2016). "In mice expressing REG3A under the RIP-1 promoter, pancreatic islets displayed normal histology and insulin secretion, yet were resistant to STZ-induced hyperglycemia and weight loss." (PMID 40723277, 2025). "This regulation is particularly important in diabetic skin inflammation, where hyperglycemia impairs IL-33-dependent REG3A expression, leading a delayed wound healing." (PMID 40723277, 2025). "It has been reported that hyperglycemia suppresses the expression of IL-33 in a diabetic mouse wound excision model and decreases the expression of REG3A in keratinocytes, thereby increasing inflammation in skin wounds." (PMID 36550940, 2022). "Collectively, these data demonstrate that hyperglycaemia inhibits IL-17 to induce IL-33 expression, thus leading to defective REG3A expression in the skin wounds of diabetic patients." (PMID 27830702, 2016). "REG3A has also been shown to be altered by mild hyperglycemia." (PMID 38717484, 2024). "REG3A reduces hyperglycemia and dyslipidemia in prediabetes and type 2 diabetes in obese rodents." (PMID 36918710, 2023). "However, hyperglycemia blocked REG3A-SHP-1 signaling, leading to increased JNK2 phosphorylation and excessive TNF-α and IL-6 levels in diabetic skin wounds after 1 h or 24 h of treatment." (PMID 34811636, 2022). "Furthermore, IL-33 was found to be involved in IL-17-induced REG3A expression; hyperglycemia could inhibit this pathway, leading to decreased REG3A expression in diabetic patients." (PMID 34811636, 2022).
inflammatory bowel disease (7 papers, 2019 to 2025). A spectrum of small and large bowel inflammatory diseases of unknown etiology. "Similar findings have been reported in humans, where serum REG3A has poor accuracy for the diagnosis of active inflammatory bowel disease (IBD)." (PMID 40392915, 2025). "This parallels findings in humans, where patients with inflammatory bowel disease have only mildly higher REG3A concentrations, whereas patients with AP and sepsis often have markedly higher REG3A and REG1A concentrations in comparison with healthy volunteers." (PMID 40392915, 2025). "Reg3α plasma levels have been reported to be a predictor of graft vs host disease and elevated in people with inflammatory bowel diseases and obesity." (PMID 31339004, 2019). "Interestingly, REG3α plasma levels have been demonstrated to correlate with disease activity in inflammatory bowel disease and in intestinal GvHD." (PMID 36883565, 2023). "REG3A is overexpressed in colonic tissues of patients with inflammatory bowel disease, and the detection of REG3A in serum could help distinguish mucosal enteropathy from functional enteropathy." (PMID 37496049, 2023).
Obesity (7 papers, 2019 to 2025). Accumulation of substantial excess body fat. "The persistence of these patterns after adjustment for inflammatory markers suggests that REG3α may be linked to obesity-related immune activation, although the study’s limited sample size likely reduced statistical power to detect modest effects." (PMID 41614735, 2025). "Obesity results from a complex interaction between metabolic, inflammatory, microbial, and environmental factors, where REG3A and IL-22 play a partial role." (PMID 41027972, 2025). "Understanding REG3α within the inflammatory landscape of obesity requires examining accompanying immune and mucosal markers." (PMID 41614735, 2025). "The parallel regulation of REG3α, IL-6, and β-defensin-2 suggests that obesity-related inflammation extends beyond adipose tissue, involving the intestinal epithelium as both a source and a target of immune signaling." (PMID 41614735, 2025). "In this cross-sectional study, we aimed to examine circulating REG3α levels in infection-free adults with obesity, overweight, and normal weight, and to explore their associations with vitamin D supplementation and biomarkers of inflammation and dysbiosis." (PMID 41614735, 2025). "Despite these connections, the role of REG3α in obesity, where low-grade inflammation and microbial imbalance coexist, remains largely unexplored." (PMID 41614735, 2025). "We aim to compare the effects of REG3A and IL-22 expression by the epithelial cells on the development of obesity-related conditions and the composition of the microbiota." (PMID 41027972, 2025). "The present study aimed to characterize circulating REG3α concentrations in adults with obesity, overweight, and normal-weight controls, and to examine their associations with vitamin D status, supplementation, and biomarkers of inflammation and dysbiosis." (PMID 41614735, 2025). "Here we show that an increase in human REG3A improves glucose and lipid homeostasis in nutritional and genetic mouse models of obesity and type 2 diabetes." (PMID 36918710, 2023). "Feeding REG3A transgenic and WT mice fatty diets resulted in comparable levels of induced obesity among them." (PMID 36918710, 2023). "Similar effects of reduced insulin hypersecretion and dyslipidemia are observed with REG3A transgenic mice during aging and obesity after feeding with a high-fat diet." (PMID 36918710, 2023). "Most importantly, in the patients with obesity and T2D, we observed significantly reduced Reg3α expression, together with evidence of attenuated intestinal AMPK T172 phosphorylation suggestive of its activity." (PMID 35241650, 2022). "The trend toward higher REG3α levels in participants with overweight, followed by a modest decline in obesity, may represent a biphasic compensatory response." (PMID 41614735, 2025). "Together, these findings suggest that REG3α may participate in pathways of mucosal–systemic immune activation in obesity and could be responsive to vitamin D–related immune modulation." (PMID 41614735, 2025). "Because REG3A is a ROS scavenger, we wondered whether REG3A’s ability to counteract oxidative damage, particularly in muscle, could help improve glucose homeostasis, which is chronically impaired by high-fat diets and obesity." (PMID 36918710, 2023). "REG3α concentrations were numerically, but not statistically, higher in individuals with overweight and obesity compared to controls, while vitamin D supplementation was associated with lower levels across models." (PMID 41614735, 2025).
acute liver failure (5 papers, 2015 to 2025). Rapid deterioration of liver function causing encephalopathy and coagulopathy. "In acute liver failure, REG3A binds to fibrin scaffolds in necrotic areas of the liver, where it reduces ROS levels and promotes hepatocyte survival." (PMID 40723277, 2025). "The beneficial effect of Reg3α on acute liver failure was reported in mice." (PMID 32517345, 2020). "The human C-type lectin Reg3α, referred to as ALF-5755, improved survival in an animal model of acute liver failure and was well tolerated in a phase 1 trial in humans." (PMID 26983031, 2016).
chronic GVHD (5 papers, 2017 to 2024). "In summary, rs7588571 genotype was associated with the expression level of REG3A mRNA and REG3A protein and the incidence of extensive chronic GVHD in patients who had received an HLA-matched sibling bone marrow transplant." (PMID 28945764, 2017). "The study cohort of patients who had diagnosis and staging of chronic GVHD based on the NIH criteria may enable us to perform more precise and comprehensive analysis of the association between REG3A polymorphism and chronic GVHD." (PMID 28945764, 2017). "In GVHD pathology, higher levels of REG3A were found to clinically differentiate the severity of rejection disease and predict transplant-related mortality in acute and chronic GVHD." (PMID 39337456, 2024). "Pre-HCT levels of REG3A in the pasireotide group (implicated as a marker for GI GVHD) were also associated with the development of chronic GVHD." (PMID 34170918, 2021). "Two factors, Reg3a and Elafin, have recently been used as biomarkers of GVHD suggesting involvement in chronic GVHD." (PMID 30479692, 2018). "The REG3A rs7588571 non-GG genotype showed a trend toward a higher incidence of extensive chronic GVHD than the GG genotype (45% vs. 24%, P = 0.087)." (PMID 28945764, 2017).
graft versus host disease (5 papers, 2019 to 2024). An immune system disorder that occurs after allogeneic hematopoietic stem cell transplant and is a reaction of donor immune cells against host tissues. "REG3A expression has been linked to multiple pathologies, such as cancers, diabetes, pancreatitis and graft-versus-host disease." (PMID 39337456, 2024). "Previous studies reported that increasing REG3α level was always observed in patients with enteropathies, such as Crohn's and celiac diseases, ulcerative colitis, and graft-versus-host disease." (PMID 34722779, 2021). "Besides its antibacterial activity, REG3A serves as a survival signal to prevent apoptosis of crypt cells with graft-versus-host disease (GVHD) in allogeneic bone marrow transplantation." (PMID 31696115, 2019).